MFAP2 (microfibril associated protein 2)
Description:
Component of the elastin-associated microfibrils.
Synonyms: MAGP; MAGP-1; MAGP1
Tractability: Antibody: its Gene Ontology location is reachable by antibodies, with high confidence; UniProt places it where antibodies can reach, with medium confidence; UniProt predicts a signal peptide or a membrane-spanning region.
Gene: Protein-coding gene on chromosome 1 (16,974,498 to 16,981,616, reverse strand). Ensembl gene ENSG00000117122.
Subcellular location: Secreted, extracellular space, extracellular matrix
Pathways (Reactome):
Extracellular matrix organization: Elastic fibre formation; Molecules associated with elastic fibres
Gene Ontology:
Molecular function: protein binding; extracellular matrix structural constituent; fibrinogen binding; fibronectin binding
Biological process: embryonic eye morphogenesis; post-embryonic eye morphogenesis; positive regulation of cold-induced thermogenesis
Cellular component: extracellular matrix; microfibril; extracellular region; non-collagenous component of interstitial matrix
Genetic constraint (gnomAD): Loss-of-function variants: 22 observed, 29.5 expected, observed/expected ratio (o/e) 0.75, 90% interval 0.53 to 1.07. The upper end of that interval is the gene's LOEUF score, 1.07, which puts it in group 4 of 6, group 1 being the genes least tolerant of losing a copy. Missense variants: 176 observed, 196.05 expected, observed/expected ratio (o/e) 0.9, 90% interval 0.79 to 1.02. Synonymous variants: 58 observed, 73.06 expected, observed/expected ratio (o/e) 0.79, 90% interval 0.64 to 0.99.
Homologues: Orthologues: chimpanzee MFAP2 (97% identical), macaque MFAP2 (97% identical), dog MFAP2 (94% identical), pig MFAP2 (92% identical), mouse Mfap2 (90% identical), guinea pig MFAP2 (87% identical), rat Mfap2 (74% identical), tropical clawed frog mfap2 (62% identical). Paralogues in human: MFAP5 (27% identical).
Diseases named in the same sentence as MFAP2 in open-access papers:
MFAP2 is named in the same sentence as 74 diseases in open-access papers, as found by Europe PMC text mining. Sharing a sentence is not in itself a finding about the gene and the disease. The quoted sentences say what the papers report.
gastric cancer (18 papers, 2019 to 2025). A primary or metastatic malignant neoplasm involving the stomach. "The study highlights that MFAP2-positive CAFs can be used as a prognostic marker for poor survival and resistance to adjuvant chemo/chemoradiotherapy and immunotherapy in gastric cancer." (PMID 38562556, 2024). "MFAP2 was reported to promote EMT by activating TGF‐β/SMAD2/3 signalling pathway in gastric cancer cells." (PMID 37635348, 2023). "Another study showed that MFAP2 encouraged cell migration and invasion in gastric cancer by enhancing the PI3K‐Akt pathway." (PMID 36583532, 2023). "An increase expression of MFAP2 was observed in several malignant tumour tissues, including gastric cancer, head and neck squamous cell carcinomas and papillary thyroid cancer." (PMID 37635348, 2023). "In gastric cancer, RT-qPCR, western blotting, and immunohistochemistry analysis confirmed that MFAP2 mRNA and protein expression levels in tumor tissues were significantly higher than those in the adjacent tissues." (PMID 36530974, 2022). "Studies have shown that MFAP2 is highly expressed in gastric cancer tissues, and its high expression is significantly related to the overall and disease-free survival of patients with gastric cancer." (PMID 35211173, 2022). "MFAP2 modulates gastric cancer cell proliferation through integrin-stimulated focal adhesion kinase activation." (PMID 36530974, 2022). "In the specific analysis of each cancer, as a pivotal gene related to tumorigenesis, MFAP2 is a biomarker for the diagnosis and prognosis of gastric cancer." (PMID 36530974, 2022). "It has been reported that in gastric cancer, MFAP2 plays an important role in regulating the integrin signaling pathway in tumor cell ECM interaction as an integrin/FAK/ERK1/2 signaling activator during gastric cancer progression." (PMID 36530974, 2022). "MFAP2 has the potential to be considered an oncogene, triggering EMT and causing cancer progression, with diagnostic capability in gastric cancer." (PMID 35333898, 2022). "MFAP2 expression level in different gastric cancer cell lines is higher than that in gastric epithelial-derived cell lines." (PMID 36530974, 2022). "It has been reported in gastric cancer that MFAP2 knockdown significantly reduced TGF-β expression and activity, as assessed by Smad-2 and Smad-3 phosphorylation." (PMID 36530974, 2022). "For instance, MFAP2 promotes motility of cancer cells through the integrin α5β1/FAK/ERK pathway in gastric cancer." (PMID 36204318, 2022). "MFAP2 expression was upregulated in gastric cancer organization and cell lines, and its downregulation inhibited AGS and HGC-27 cell wound healing, migration, and invasion." (PMID 36530974, 2022). "The ability of MFAP2 in activating TGF-β/SMAD2/3 pathway in gastric carcinoma has also been reported, and this activation accelerates the transformation of gastric carcinoma from an epithelial cell phenotype to a mesenchymal phenotype." (PMID 35211173, 2022). "Upregulation of MFAP2 in gastric carcinoma has been found, in which MFAP2 accelerates cancer cell migration via MFAP2/integrin α5β1/FAK/ERK pathway." (PMID 35211173, 2022). "MFAP2 stimulates epithelial–mesenchymal transition in gastric cancer cells by activating TGFβ signaling pathway that supports survival and metastasis of endometrial cancer cells." (PMID 31552087, 2019). "Furthermore, MFAP2 was found to promote epithelial–mesenchymal transition of gastric cancer cells by activating TGF‐β/SMAD2/3 signalling pathway." (PMID 37635348, 2023). "MFAP2 gene shares its oncogenic role not only in gastric cancer but also in breast cancer." (PMID 35333898, 2022). "A previous study pointed out that MFAP2 is a novel microRNA-29 target, and miR-29/MFAP2/integrinα5β1/FAK/ERK1/2 might be an important carcinogenic pathway in gastric cancer progression." (PMID 35211173, 2022).
gastric cancer (continued). "Furthermore, it has been proposed that MFAP2 might improve the transition between epithelial and mesenchymal in gastric carcinoma via activating the TGF-β/SMAD2/3 pathway." (PMID 38822944, 2024). "In gastric cancer (GC), SERPINB5 upregulates ITGB1 and promotes epithelial mesenchymal transition (EMT), while MFAP2 also upregulates ITGB1." (PMID 38279122, 2024). "For example, Igf1 and Mfap2, differentially expressed in I1 state, have been shown to induce EMT in hepatocellular carcinoma and in gastric cancer cells respectively." (PMID 32870263, 2020). "To date, MFAP2 has not been evaluated in breast cancer; however, studies in gastric cancer and hepatocellular carcinomas demonstrate that it has elevated expression associated with poor outcomes." (PMID 35755802, 2022). "Bearing the prognostic value in mind, MFAP2 serves as a negative indicator for overall survival in gastric cancer." (PMID 35333898, 2022). "Furthermore, MFAP2 is found to be a possible player in TGF-β/SMAD2/3 signaling pathway activation to advance proliferation, migration, invasion, and epithelial-mesenchymal transition of gastric cancer cells." (PMID 35211173, 2022). "However, TGF-β treatment reversed MFAP2 knockdown gastric cancer cell damaged migration and invasion without changing MFAP2 expression." (PMID 36530974, 2022).
breast carcinoma (12 papers, 2011 to 2025). "Overexpression of the genes encoding these proteins is associated with poor breast cancer survival, and MFAP2 has been shown to promote cell proliferation, migration, invasion, and epithelial to mesenchymal transition." (PMID 34149812, 2021). "In addition, pan-cancer studies have also indicated that MFAP2 expression is elevated in breast cancer and may be associated with adverse prognosis in breast cancer patients." (PMID 38822944, 2024). "To determine the impact of less characterized ECMs in metaplastic TNBC, we overexpressed MFAP2 in primary metaplastic breast cancer cells and performed RNA sequencing." (PMID 41595979, 2025). "During our study, a noteworthy correlation between MFAP2 expression and breast cancer subtypes was observed." (PMID 38822944, 2024). "As an oncogene in breast cancer, MFAP2 knockout can significantly increase MCF-7 and MDA-MB-231 cell apoptosis." (PMID 36530974, 2022). "While collagen type I is well described as having a role in cancer cell proliferation, drug resistance, and motility, the matrix proteins such as COL3A1, COL11A1, FBN1, and MFAP2 are less explored in breast cancer." (PMID 35755802, 2022). "MFAP2 expression was increased in breast cancer tissues, and its overexpression predicted poor prognosis." (PMID 36530974, 2022). "In addition, the inhibition of LCPAT1 impaired the cell invasion and migration of MCF-7 and MDA-MB-231 breast cancer cells by decreasing MFAP2 expression." (PMID 36613528, 2022). "Mechanistically, LCPAT1 could recruit retinoblastoma-binding protein 4 (RBBP4) to the promoter region of microfibril-associated protein 2 (MFAP2) to induce its expression, thus contributing to breast cancer." (PMID 36613528, 2022). "In addition, the expression of MFAP2 protein increased in breast cancer, colon cancer, and lung adenocarcinoma, and decreased in clear cell renal cell carcinoma." (PMID 36530974, 2022). "Moreover, lncRNA LCPAT1 interacts with RBBP4 and recruits it to the MFAP2 promoter, promoting breast cancer progression by activating MFAP2 transcription." (PMID 36530974, 2022). "In breast cancer cells, RBBP4 interacts with lncRNA LCPAT1 to activate MFAP2, whose transcription then regulates the proliferation, migration and invasion of cancer." (PMID 38028543, 2023).
Obesity (8 papers, 2016 to 2025). Accumulation of substantial excess body fat. "In humans, genome-wide association studies (GWAS) have linked the MFAP2 locus to obesity and type 2 diabetes." (PMID 39844333, 2025). "Top genes differentially methylated between these cohorts included the obesity-protective MFAP2 gene as well as cancer risk susceptibility genes APOL3 and RNASEL." (PMID 39844333, 2025). "In obesity-associated colon cancer, the circulating concentration of MFAP2 and its gene expression in visceral adipose tissue decreased." (PMID 36530974, 2022). "It has been shown that MFAP2(−/−) mice exhibit obesity, metabolic dysfunction, adipocyte hypertrophy, and reduced heat generation." (PMID 36530974, 2022). "Significant differences in MFAP2 gene expression levels were observed, being significantly decreased due to obesity (p < 0.010) and CC (p < 0.001)." (PMID 34445187, 2021). "The treatment of Mfap2 knockout mice with antibodies neutralizing TGF-β prevented increased adiposity, proposing its role in the regulation of TGF-β in obesity and its associated comorbidities." (PMID 34445187, 2021). "Based on its relevance in obesity-associated inflammation and colon carcinogenesis, the VAT was selected to study MFAP2 and TGFB1 gene expression levels." (PMID 34445187, 2021). "MAGP1 deficiency in mice (Mfap2−/−) causes adipocyte hypertrophy in peripheral WAT, which contributes to obesity and then insulin resistance." (PMID 27445989, 2016). "Since it is widely recognized that chronic low-grade inflammation is a cardinal feature of CC local progression enhancement, we next evaluated whether well-known inflammation-related factors dysregulated in obesity influence MFAP2 expression in HT-29 cells." (PMID 34445187, 2021). "Interestingly, a significant decrease (p < 0.01) in the mRNA levels of MFAP2 in HT-29 cells preincubated with ACM from volunteers with obesity compared with control media was observed." (PMID 34445187, 2021). "Interestingly, we found a significant decrease (p < 0.01) in the expression levels of MFAP2 after incubation with the ACM obtained from volunteers with obesity." (PMID 34445187, 2021). "Finally, the impact of the adipocyte-conditioned medium (ACM) obtained from patients with obesity on the expression of MFAP2 in HT-29 cells was further analyzed." (PMID 34445187, 2021). "TGF-β activity increased in MFAP2(−/−) adipose tissue, and treating MFAP2(−/−) mice with a TGF-β-neutralizing antibody improved their body temperature and prevented the increased obesity." (PMID 36530974, 2022).
ovarian carcinoma (8 papers, 2019 to 2025). A malignant neoplasm originating from the surface ovarian epithelium. "Circulating (plasma) protein levels predicted by the MFAP2 gene were positively associated with the risk of all invasive epithelial ovarian cancers." (PMID 36530974, 2022). "The predicted circulating MFAP2 protein level is associated with epithelial ovarian cancer risk." (PMID 36530974, 2022). "In tumors, increased MFAP2 expression has been validated in papillary thyroid cancer, hepatocellular carcinoma, ovarian cancer, melanoma and laryngeal squamous cell carcinoma." (PMID 40657371, 2025). "MFAP2 overexpression significantly increased ovarian cancer cell clones’ viability and number, whereas MFAP2 knockdown produced opposite results." (PMID 36530974, 2022). "In ovarian cancer, MFAP2 promotes β-catenin transfer from the cytoplasm to the nucleus via the FoxM1/β-Catenin signal pathway, increasing the glycolysis-related gene (GLUT1 and HK2) expression levels in A2780 and SKOV3 cells." (PMID 36530974, 2022). "Similarly, MFAP2 overexpression reduced G1 phase cell proportion and increased those of S and G2/M phase cells in ovarian cancer, suggesting that MFAP2 could stimulate G1-S phase cell transition." (PMID 36530974, 2022). "MFAP2 promotes cell proliferation and glycolysis by modulating the FOXM1/β-catenin signaling pathway in ovarian cancer." (PMID 36530974, 2022). "Subsequently, the remaining prognostic biomarkers from other cancer types were also assessed by OSov, which demonstrated that these genes (SFRP4, NUAK1, MFAP2, PLIN1 and EFNB2) exhibited good performance in predicting ovarian cancer patient outcome." (PMID 35053021, 2021). "The MFAP2 mRNA and protein levels in all ovarian cancer cell lines were much higher than those in non-tumor IOSE80 cell lines." (PMID 36530974, 2022).
colon cancer (7 papers, 2019 to 2025). "mir-423-5p overexpression can downregulate MFAP2 protein expression and inhibit colon cancer cell proliferation." (PMID 36530974, 2022). "Eight significantly over‐expression genes in tumour tissues (BGN, THBS2, SPARC, CDH11, MFAP2, MMP11, SPP1 and THY1) were defined as significantly signature genes that implicated in colon cancer metastasis progress." (PMID 36377223, 2022).
hepatocellular carcinoma (7 papers, 2020 to 2025). A malignant tumor that arises from hepatocytes. "Another study has also indicated the relevance of MFAP2 in hepatic carcinoma, whereby MFAP2 overexpression in hepatic carcinoma is associated with cancer staging, poor OS, and disease-specific survival." (PMID 35211173, 2022). "Studies have shown that MFAP2 is significantly upregulated in hepatocellular carcinoma and is associated with tumor progression and prognosis." (PMID 36530974, 2022). "In contrast, MFAP2 upregulation was reported in head and neck cancer and associated with poor prognosis in gastric and hepatocellular carcinomas." (PMID 34298834, 2021). "Furthermore, repression of MFAP2 results in a loss of cellular proliferation and motility in hepatocellular carcinomas in vitro." (PMID 35755802, 2022). "In hepatocellular carcinoma, quantitative real-time PCR (RT-qPCR) analysis confirmed that MFAP2 mRNA expression was significantly upregulated in tumor tissues." (PMID 36530974, 2022). "A study on hepatocellular carcinoma cells showed that MFAP2 was significantly overexpressed in hepatocellular carcinoma cells, correlating with the cancer stage." (PMID 36530974, 2022). "An in vitro human umbilical vein endothelial cells (HUVEC) tube-forming experiment showed that vascular endothelial growth factor A decreased significantly after MFAP2 knockdown in hepatocellular carcinoma." (PMID 36530974, 2022). "MFAP2 may be a valuable prognostic marker and an effective anticancer target, as it plays a key role in the development of hepatocellular carcinoma." (PMID 36530974, 2022). "MFAP2 promotes hepatocellular carcinoma cell proliferation, migration, and invasion." (PMID 36530974, 2022). "MFAP2 may also be a promising prognostic biomarker with important clinical significance as a potential immunotherapeutic target for hepatocellular carcinoma patients." (PMID 36530974, 2022). "For example, hepatocellular carcinoma cell migration and invasion ability were reduced by inhibiting EMT-related protein expression in MHCC97H cells after MFAP2-knockdown." (PMID 36530974, 2022).
colorectal cancer (6 papers, 2022 to 2025). A primary or metastatic malignant neoplasm that affects the colon or rectum. "For the m1A eraser genes ALKBH1 and ALKBH3, it was suggested that the mRNA expression of MFAP2 and the methylation modification of m1A were increased in colorectal cancer when ALKBH1 was silenced." (PMID 37178414, 2023).
melanoma (5 papers, 2022 to 2025). A malignant, usually aggressive tumor composed of atypical, neoplastic melanocytes. "In melanoma, MFAP2 disruption influenced Wnt/β-catenin linked protein levels, and β-catenin neutralized MFAP2’s effect on EMT, as evidenced by the altered EMT molecular markers’ protein levels." (PMID 36530974, 2022). "This study showed that MFAP2 activates the Wnt/β-catenin signaling pathway and enhances EMT during melanoma metastasis.Forkhead box M1 (FoxM1) belongs to the forkhead box transcription factor family." (PMID 36530974, 2022). "MFAP2 is overexpressed in melanoma with its capacity of manipulating EMT-related proteins and Wnt/β-catenin pathway to enhance melanoma invasion and migration ability." (PMID 35211173, 2022).